NQO1 (NAD(P)H quinone dehydrogenase 1)
Diseases named in the same sentence as NQO1 in open-access papers (continued):
Sharing a sentence is not in itself a finding about the gene and the disease.
preeclampsia (2 papers, 2022 to 2025). Preeclampsia is a hypertensive disorder of pregnancy that is characterized by new-onset hypertension with proteinuria presenting after 20 weeks of gestation, and depending on mild or severe forms may initially present with severe headache, visual disturbances, and hyperreflexia. "This study is the first one to investigate the NQO1 gene polymorphism and the promoter methylation status among Iranian patients with preeclampsia." (PMID 41292553, 2025). "Therefore, this study aims to investigate the possible relationship between the NQO1 rs1800566 variants and NQO1 promoter methylation status in preeclampsia patients." (PMID 41292553, 2025). "Nevertheless, further research with larger sample sizes among various populations could help to elucidate the role of NQO1 gene variants and the NQO1 methylation in preeclampsia." (PMID 41292553, 2025). "Reduced expression of NQO1 in preeclampsia may lead to heightened susceptibility to lipid peroxidation." (PMID 41292553, 2025). "Given that the NADPH quinone oxidoreductase 1 (NQO1) is an important enzyme in the antioxidant system, this study aimed to investigate the relationship between the NQO1 rs1800566 polymorphism, NQO1 promoter methylation, and oxidative stress with the risk of preeclampsia." (PMID 41292553, 2025). "It is also important to investigate the other epigenetic modifications to assess the expression regulation of NQO1 in preeclampsia." (PMID 41292553, 2025). "The mean methylation rate of NQO1 was 44.75 ± 35.80% in all patients with preeclampsia compared to 45.50 ± 31.21% (p = 0.91) in controls." (PMID 41292553, 2025). "Western blot analysis revealed that the expression levels of NQO1 in placental tissues from patients with preeclampsia were significantly lower than normal control placentas (p < 0.05)." (PMID 36061193, 2022). "Regarding the potential of markers for discriminating preeclampsia patients from normal pregnant women, the ROC analysis revealed that the AUC values of the NQO1, SRXN1, CDO1, EGFR, FBXW7, and JUN are 0.803, 0.748, 0.708, 0.703, 0.665, and 0.681, respectively." (PMID 36061193, 2022). "Immunohistochemistry analysis of placenta tissues showed that the NQO1 expression decreased in preeclampsia, whereas SRXN1 expression increased." (PMID 36061193, 2022). "The present study observed the absence of a link between the NQO1 rs1800566 variants and susceptibility to preeclampsia and the lack of an association between NQO1 methylation status with the risk of preeclampsia." (PMID 41292553, 2025). "It seems the NQO1 rs1800566 and the promoter methylation of NQO1 gene are not involved in the risk of preeclampsia." (PMID 41292553, 2025). "Numerous studies have shown that NQO1 plays a crucial role in the antioxidant defense mechanisms, however, how NQO1 regulates ferroptosis in preeclampsia still needs to be further studied." (PMID 36061193, 2022). "Moreover, the protective role of NQO1 has been shown in some diseases that are associated with high blood pressure, but its specific involvement in preeclampsia has not been well investigated." (PMID 41292553, 2025). "Although it has been shown that the expression of the NQO1 gene in placenta tissue decreases in preeclampsia, no study has been conducted on the regulation of the gene expression and the methylation status of this gene." (PMID 41292553, 2025). "Our study demonstrated the absence of correlation between NQO1 rs1800566 and preeclampsia among Iranian women." (PMID 41292553, 2025).
promyelocytic leukemia (2 papers, 2015 to 2021). "In order to explore the anticancer activity based on interaction between limonin and NQO1, Human promyelocytic leukemia cells (HL‐60) were studied in vitro." (PMID 33841805, 2021).
prostate adenocarcinoma (2 papers, 2020 to 2023). "Given the conflicting but critical role of NQO1 that influences cancer progression, we demonstrate that NQO1 knockdown cells rapidly develop into advanced prostate adenocarcinoma." (PMID 31909204, 2020). "Similarly, patients with high NQO1 mRNA expression for PFI of those cancers had poorer outcomes except for prostate adenocarcinoma." (PMID 37583897, 2023). "Conversely, high NQO1 mRNA expression has a protective effect for OS in Sarcoma, PFI, and DSS for prostate adenocarcinoma." (PMID 37583897, 2023).
Rb (2 papers, 2019 to 2023). "Therefore, the detection of the pathogenic variant of the gene NQO1 in four patients from two different families suggested that it might be associated with the pathogenesis of Rb." (PMID 31207142, 2019). "This is the first study suggesting that these genes, FGFR4, NQO1, ACADS CX3CR1, GBE1, KRT85, and TYR genes, may play a role in the etiology of Rb." (PMID 31207142, 2019).
rhinitis (2 papers, 2021 to 2025). An inflammation of the mucous membrane lining the nose, usually associated with nasal discharge. "The administration of ALA protected against rhinitis by decreasing ROS production in human nasal fibroblasts via NQO1 pathways." (PMID 40429916, 2025).
serous carcinoma (2 papers, 2015 to 2019). "The rate of positive NQO1 protein expression was significantly higher in serous carcinomas (85.6%, 137/160) than in borderline serous tumors (56.5%, 35/62) or benign serous tumors (34.0%, 18/53) (P < 0.01, respectively)." (PMID 25885439, 2015). "We observed that expression of NQO1 protein (positive and strongly positive) was significantly higher in serous carcinomas compared with either borderline or benign serous tumors (P < 0.01)." (PMID 25885439, 2015). "However, when exploring the TCGA CNH group, we observed a significantly lower NQO1 mRNA level in serous carcinoma, compared to endometrioid carcinoma." (PMID 30908539, 2019). "Similarly, the rate of strong, positive NQO1 protein expression was significantly higher in serous carcinomas (63.8%, 102/160) than in either borderline serous tumors (32.3%, 20/62) or benign serous tumors (11.3%, 6/53) (P < 0.01, respectively)." (PMID 25885439, 2015).
serous ovarian carcinoma (2 papers, 2015 to 2022). "Compatible with these findings, we also observed that the rate of strongly positive NQO1 protein expression was significantly higher in patients with late-stage serous ovarian carcinoma, compared with early-stage cases." (PMID 25885439, 2015). "We also assessed the prognostic value of high NQO1 expression in patients with serous ovarian carcinoma." (PMID 25885439, 2015). "In the present study, we investigated the correlation between high expression of NQO1 and clinicopathological features of serous ovarian carcinomas." (PMID 25885439, 2015). "In keeping with these results, analysis of NQO1 mRNA levels by qRT-PCR confirmed elevated levels of NQO1 transcript in serous ovarian carcinoma samples compared with benign ovarian tumors in fresh tissues." (PMID 25885439, 2015). "Univariate survival analysis revealed that tumor histological grade, FIGO stage and NQO1 expression status were all significantly related to OS of patients with serous ovarian carcinoma (P < 0.05)." (PMID 25885439, 2015). "qRT-PCR analysis also confirmed increased levels of NQO1 mRNA in serous ovarian carcinoma samples compared with benign ovarian tumors in fresh tissues." (PMID 25885439, 2015). "Our clinical and experimental data indicate that NQO1 is a prognostic factor and a potential therapeutic target in patients with serous ovarian carcinoma." (PMID 25885439, 2015). "NQO1 protein expression was assessed using immunohistochemical (IHC) staining in 160 patients with serous ovarian carcinoma, 62 patients with ovarian borderline tumors and 53 patients with benign ovarian tumors." (PMID 25885439, 2015). "This study aimed to investigate the clinicopathological significance of high NQO1 expression in serous ovarian carcinoma." (PMID 25885439, 2015). "Here, we performed IHC staining of NQO1 protein using 160 serous ovarian carcinomas, 62 borderline serous tumors and 53 benign serous tumors." (PMID 25885439, 2015). "High expressin of NQO1 protein may be an effective biomarker for poor prognostic evaluation of patients with serous ovarian carcinomas." (PMID 25885439, 2015). "NQO1 may serve as a new prognostic factor and potential therapeutic target for patients with serous ovarian carcinoma." (PMID 25885439, 2015).
status epilepticus (2 papers, 2021 to 2024). Status epilepticus is defined as a continuous seizure lasting more than 30 min, or two or more seizures without full recovery of consciousness between any of them. "The expressions of nuclear Nrf2, HO-1, and NQO1 were upregulated 24 h after the onset of lithium chloride-pilocarpine-induced status epilepticus in sixty male Sprague–Dawley rats." (PMID 38167027, 2024). "Enhancement of nuclear Nrf2, NQO1, and HO-1 by the application of hydroxylated fullerenes, known as a potent free radical scavenger, significantly reduced lipid peroxidation and apoptosis in the hippocampus of rats following status epilepticus." (PMID 38167027, 2024). "Furthermore, using an adeno-associated virus to overexpress human Nrf2, the expression levels of Nrf2 and NQO1 increased progressively in mice, reaching a peak at 72 h after pilocarpine-induced status epilepticus." (PMID 38167027, 2024). "Nrf2 expression levels, along with the three Nrf2-regulated genes HO-1, NQO1, and GST, exhibited a notable increase in mice with status epilepticus." (PMID 38167027, 2024).
subarachnoid hemorrhage (2 papers, 2017 to 2025). A serious neurological disorder characterized by intracranial hemorrhage into the subarachnoid space. "Melatonin exerts its effects through the MT2 receptor, activating Nrf2 and downstream genes such as HO-1/NQO1 to inhibit ferroptosis in neuronal injury induced by subarachnoid hemorrhage, leading to improved neurological function in rats." (PMID 39959423, 2025).
thalassemia (2 papers, 2018 to 2024). An inherited blood disorder characterized by a decreased synthesis of one of the polypeptide chains that form hemoglobin. "The influence of treosulfan and S, S-EBDM exposure, and GSTA1/NQO1 polymorphisms on graft rejection, RRTs, chimerism status, and 1-year overall survival (OS), and thalassemia-free survival (TFS) were assessed." (PMID 37846495, 2024).
type 1 diabetes (2 papers, 2024). "Using the streptozotocin-induced type 1 diabetes model, the authors found that eugenol increased the expression of Nrf2-regulated HO-1 and NAD(P)H quinone dehydrogenase 1 (NQO-1), and that this effect led to reduced β-cell damage." (PMID 39598416, 2024).
uveal melanoma (2 papers, 2023 to 2025). A melanoma derived from melanocytes of the uveal tract. "The levels of NQO1 mRNA were negatively correlated with CD4 T cells and CD8 T cells in testicular germ cell tumors and positively associated with CD4 T cells and CD8 T cells in uveal melanoma and ovarian serous cystadenocarcinoma." (PMID 37583897, 2023).
acral melanomas (1 paper, 2022). "Over expression of NQO1 in acral melanomas and human melanocytes is reported to increase tyrosinase activity, but the extent to which this and other antioxidant enzymes contribute to the effects of SFN on pigment cells has not been determined." (PMID 36291795, 2022).
acute GVHD (1 paper, 2024). "There was a trend for low treosulfan AUC(0–∞) to be associated with rejection (hazard ratio (HR) (95% confidence interval (CI)) = 0.08 (0, 1.37); P = 0.08); four covariates were significant by association with 1-year mortality (GSTA1, NQO1 polymorphisms, incidence of acute GVHD and hepatic SOS)." (PMID 37846495, 2024).
Acute hepatic failure (1 paper, 2022). Hepatic failure refers to the inability of the liver to perform its normal synthetic and metabolic functions, which can result in coagulopathy and alteration in the mental status of a previously healthy individual. "In the existing study, the gene expression levels of Nrf2, HO-1 and NQO-1 were augmented in the APAP-induced acute hepatic failure, whereas pretreatment with CARD extract caused further augmented Nrf2, HO-1 and NQO-1." (PMID 36354677, 2022).
Age-related cataract (1 paper, 2015). A type of cataract (opacification of the lens) that forms during the course of aging. "In addition, compared to indoor work places and the CC genotype of NQO1, outdoor work places and CT/TT genotypes of NQO1 were found to increase the risk of age-related cataracts (OR=2.75, 95%CI: 1.20-6.33, P=0.017)." (PMID 27844006, 2015).
alcohol (1 paper, 2022). "Ursolic acid, a triterpenoid and a strong Nrf2 activator, protected against chronic alcohol liver injury by inducing Nqo1, Gclc and glutathione S-transferases." (PMID 35565941, 2022).
alcoholic liver damage (1 paper, 2025). "The downstream target genes of Nrf2, such as HO-1 and NQO1, also play important roles in relieving alcoholic liver damage." (PMID 40219012, 2025).
atrial fibrillation (1 paper, 2018). A disorder characterized by an electrocardiographic finding of a supraventricular arrhythmia characterized by the replacement of consistent P waves by rapid oscillations or fibrillatory waves that vary in size, shape and timing and are accompanied by an irregular ventricular response. "We aimed to assess impact of three important genes participating in vitamin K cycle (i.e. VKORC1 rs9923231, CYP4F2 rs2108622 and NQO1 rs1800566) on the daily stable warfarin dose requirement in Sichuan Han Chinese patients with catheter ablation of atrial fibrillation." (PMID 29776386, 2018).
autoimmune Experimental autoimmune encephalomyelitis (1 paper, 2022). "Nqo1-deficient mice showed ameliorated symptoms in a Th17-dependent autoimmune Experimental autoimmune encephalomyelitis (EAE) model." (PMID 35905076, 2022).
Autoimmunity (1 paper, 2011). The occurrence of an immune reaction against the organism's own cells or tissues. "Nqo1 is a cytosolic enzyme that catalyzes the metabolic reduction of quinines and derivatives and is an endogenous factor in the regulation of immune response and autoimmunity." (PMID 21799680, 2011).
bladder tumours (1 paper, 2001). "Elevated NQO1 levels in human bladder tumour tissue exist in a subset of patients as measured by both immunohistochemical and enzymatic assays." (PMID 11710826, 2001).
bladder urothelial carcinoma (1 paper, 2023). "Bladder urothelial carcinoma had the highest frequency (approximately 3%) of NQO1 alteration." (PMID 37583897, 2023). "Besides, HR for NQO1 was significantly increased for the PFI of rectum adenocarcinoma and bladder urothelial carcinoma and DSS of kidney renal clear cell carcinoma." (PMID 37583897, 2023).
bone marrow failure syndrome (1 paper, 2025). "Notably, genetic polymorphisms in detoxification enzymes such as glutathione S-transferases (GSTs) and NAD(P)H: quinone oxidoreductase 1 (NQO1) have been investigated for their potential role in modulating individual risk for various malignancies and bone marrow failure syndromes." (PMID 41001332, 2025).
brain tumors (1 paper, 2024). "Fluorescent probes have also been developed to enable non-invasive monitoring of endogenous NQO1 activity in brain tumor cells both in vitro and in transplanted tumors in nude mice." (PMID 38167027, 2024). "NQO1 contributes to various dimensions of tumorigenesis and treatment response in various brain tumors." (PMID 38167027, 2024). "Furthermore, the expression levels of NQO1 can impact the efficacy of tumor treatment in specific types of brain tumors." (PMID 38167027, 2024).
brainstem gliomas (1 paper, 2024). "The modulation of the elevated levels of NQO1 in tumors suggests a potential method to enhance the efficacy of radiotherapy in brainstem gliomas." (PMID 38167027, 2024).
brucellosis (1 paper, 2025). Brucellosis is a bacterial infection that spreads from animals to people via unpasteurized dairy products or by exposure to contaminated animal products or infected animals. "Conversely, GPX1, NOS, NQO1 and Nrf2 genes were significantly downregulated in brucellosis-infected does compared to the non-infected." (PMID 39825331, 2025).
cervical (1 paper, 2014). "On univariate analysis, patients with high-level NQO1 expression cervical SCC tumors had significantly lower DFS and OS rates (P = 0.001 and P = 0.027, respectively) than those with low-level NQO1 expression tumors." (PMID 24912939, 2014).
cervical intraepithelial neoplasia (1 paper, 2015). "In a previous study, a strong positive rate of NQO1 protein expression in both SCCs (54.80%) and cervical intraepithelial neoplasia (CINs) (27.59% in CIN-1, 34.21% in CIN-2 and 40.74% in CIN-3) was significantly higher than in the normal cervix (4%)." (PMID 28983331, 2015).
cervical tumor (1 paper, 2014). "Even in light of this recent information, the molecular mechanism of NQO1 responsible for cervical tumor progression remains to be elucidated, and additional studies are warranted to further our understanding of the role that NQO1 plays in cervical tumorigenesis." (PMID 24912939, 2014).
chronic fatigue syndrome (1 paper, 2020). "In contrast, in patients with chronic fatigue syndrome, NQO1 was downregulated." (PMID 32614880, 2020).
chronic hepatitis B (1 paper, 2019). "Associations of miR-122 expressed in liver and anti-oxidant genes, such as heme oxygenase 1 (HMOX-1), NAD(P)H, quinone oxidoreductase-1 (NQO1), and growth factor erv1-like (GFER1) in liver tissue specimens obtained from patients with chronic hepatitis B, have been uncovered." (PMID 31640265, 2019).
Clear Cell Renal Cell Carcinoma (1 paper, 2024). "Unlike our findings, they found that DPP9 inhibited ferroptosis and induced sorafenib resistance in Clear Cell Renal Cell Carcinoma not by regulating the NRF2 downstream target gene NQO1, but by regulating SLC7A11." (PMID 39094401, 2024).
cyst (1 paper, 2014). A sac-like closed membranous structure that may be empty or contain fluid or amorphous material. "Furthermore, NQO1 was strongly expressed in the cyst epithelium of MADISH patients." (PMID 24503019, 2014). "Indeed, we detected strong expression of SPRR2, SLPI, EPGN and of the classical NRF2 target NQO1 in the epidermis and cyst epithelium of MADISH patients, with particularly strong staining of SPRR2, SLPI, and NQO1 in differentiated keratinocytes." (PMID 24503019, 2014). "Indeed, we found strong expression of NQO1, SLPI, SPRR2, and EPGN in the affected epidermis and cyst epithelium of these patients." (PMID 24503019, 2014).
dependence (1 paper, 2021). "The quinone oxidoreductase 1 (NQO1) gene was involved in the pathophysiological process of illicit drugs abuse, and its polymorphisms might be associated with methamphetamine (METH) dependence susceptibility." (PMID 34467676, 2021). "NQO1 was likely to be a positional candidate gene of illicit drug dependence." (PMID 34467676, 2021).
diabetic cardiomyopathy (1 paper, 2019). Diabetic cardiomyopathy is a disorder of the heart muscle in people with diabetes. "As expected, H2S could activate the Nrf2 signaling pathway together with the upregulations of antioxidant proteins haem oxygenase-1 (HO-1) and NAD(P)H: quinone oxidoreductase 1 (NQO1), thus alleviating the development of diabetic cardiomyopathy via attenuation of oxidative stress in the heart." (PMID 31390847, 2019).
E. coli infection (1 paper, 2019). "Consistently, overexpressing Keap14A, but not Keap1WT or Keap14D also profoundly downregulated the Nrf2 protein levels, as well as the mRNA and protein levels of Nqo1 or Ho-1 genes, in Raw264.7 cells with E. coli infection." (PMID 30765703, 2019).
endometrial tumour (1 paper, 2017).
esophageal tumor (1 paper, 2013). "Similar to our study, other reports have also shown an association of NQO1 609C > T polymorphism with susceptibility to esophageal tumors." (PMID 23497461, 2013).